CCR2 (C-C motif chemokine receptor 2)
Diseases named in the same sentence as CCR2 in open-access papers (continued):
Sharing a sentence is not in itself a finding about the gene and the disease.
myocardial infarction (continued). "Monocyte chemoattractant protein-1 (MCP-1) and its receptor, CCR2, which is preferentially expressed on human and murine monocytes, are involved in the early inflammatory reaction after myocardial infarction." (PMID 34040032, 2021). "Another chemokine radiotracer is 68Ga-DOTA-ECL1i which targets the CCR2 (C-C chemokine receptor type 2) and was found to be localized to tissue injury sites in mouse models of cardiomyocyte ablation and myocardial infarction." (PMID 34485416, 2021). "NPs were co-localized in monocytes lowered the migratory capacity of monocytes toward MCP-1.The silencing of CCR2 reduces the myocardial infarct size after coronary artery occlusion and reduced the number of monocytes/macrophages by 82%." (PMID 33703990, 2021). "In contrast, depletion of resident cardiac CCR2- macrophages in a murine model of myocardial infarction increased infarct area, reduced LV systolic function, and exaggerated LV remodeling." (PMID 32349267, 2020). "CCR2, the receptor for CCL2 and CCL11, is expressed on HSPCs and CCR2-positive HSCs were found to be the most upstream contributor to emergency myelopoiesis, after myocardial infarction." (PMID 33003401, 2020). "HSPCs expressing CCR2 were recruited to sites of peripheral inflammation, such as a damaged liver or myocardial infarction, to help repair inflamed tissues." (PMID 27123008, 2016). "Reduction of inflammatory CCR2+ monocytes either using a knockout model of CCR2 or an antibody-mediated approach attenuated the inflammatory response after myocardial infarction and had beneficial effects on cardiac remodeling." (PMID 25904868, 2015). "Carriers of an experimentally confirmed damaging CCR2 variant are at a lower lifetime risk of myocardial infarction and coronary artery disease without carrying a higher risk of infections." (PMID 37645892, 2024). "In conclusion, we found that heterozygous carriers of a rare damaging CCR2 variant are at lower lifetime risk of myocardial infarction and coronary artery disease without carrying a higher risk of infections." (PMID 37645892, 2024). "Similarly, in adult mice after myocardial infarction, there is a significant influx of Ccr2-expressing macrophages at 3 days post injury, which coincides with an increase in Il1b expression." (PMID 36271843, 2023). "CCR2−/− mice, which exhibit reduced inflammatory monocyte recruitment, showed preserved heart function and reduced infarction size after the induction of myocardial infarction." (PMID 36498897, 2022). "In fact, CCR2 signaling promotes adverse remodeling in myocardial infarction, which was reversed upon ACKR2 upregulation, indicating that the scavenging of CC chemokines by ACKR2 regulates tissue homeostasis and favorable cardiac remodeling after MI and limits pathogenic inflammation." (PMID 35677043, 2022). "Activation of CCR2+ macrophages leads to the upregulation of inflammatory chemokines and cytoplasmic inflammatory factors, exacerbating the apoptosis of cardiomyocytes after myocardial infarction." (PMID 36618351, 2022). "Silencing (at least for one week) of CCR2 in ischemia/reperfusion reduces myocardial infarct size." (PMID 34040032, 2021). "CCR2+ monocytes, peaking at 7 days in models of spinal cord injury and myocardial infarction." (PMID 25469644, 2014). "In the heart, an organ with abundant resident macrophages that are established during embryonic development, it was found that CCR2+ Ly6-Chi monocyte-derived macrophages coordinate the inflammatory response after cardiac injury by AngII infusion or myocardial infarction (MI)." (PMID 25352845, 2014). "However, analysis of published scRNA-seq data indicates a rapid influx of Ccr2-expressing macrophages 1 day post myocardial infarction coincident with elevated Tnfa and Il1b expression, an event that may have been missed previously." (PMID 36271843, 2023).
myocardial infarction (continued). "Interestingly, another research found that overexpression of CCL2 (the ligand of CCR2) in the heart induces massive infiltration of CCR2+ monocytes and macrophages, which can promote cardiac angiogenesis and improve left ventricular dilatation and dysfunction after myocardial infarction." (PMID 36196399, 2022). "Previous work using other models of cardiac injury such as myocardial infarction, pressure overload or hypertension, describe a first wave of macrophages being derived from Ly6Chi inflammatory monocytes, which can be abrogated in CCR2−/− mice due to impaired bone marrow egress." (PMID 35090403, 2022). "However, resident CCR2+ macrophages compared to recruited CCR2+macrophages differentially express type I IFN-stimulated genes in response to myocardial injury, which suggests that CCR2+-resident macrophages are responsive to type I interferon produced during myocardial infarction." (PMID 33396359, 2020). "During inflammatory processes, monocyte recruitment, which is tightly regulated by interaction between CCL2 and CCR2, could be reduced using silencing of the chemokine CCR2 with nanoparticles, as already experimentally tested in experimental myocardial infarction." (PMID 30177883, 2018). "Our results are also consistent with reduced stiffness as a requirement for a improved functional outcome after myocardial infarction (CCR1−/− and CCR2−/−)." (PMID 36498897, 2022). "We performed myocardial infarction in CCR1−/− (reduced neutrophils recruitment) mice, CCR2−/− (reduced inflammatory monocyte recruitment) mice, CCR5−/− (reduced T-cell recruitment) mice and CX3CR1−/− mice (reduced reparatory monocyte recruitment) mice." (PMID 36498897, 2022). "To further investigate whether Lyve1-Cre-S1pr1flox/wt mice influenced cardiac resident macrophage after myocardial infarction, we performed co-immunostaining of CCR2 and F4/80 in post-MI hearts." (PMID 36003911, 2022). "Under myocardial infarction conditions, the monocytes released by spleen will be recruited to heart through MCP-1/CCR2 interaction." (PMID 31824322, 2019). "Using a mouse model of myocardial infarction (MI), Nahrendorf's group demonstrated that myeloid-biased, CCR2+ HSPCs increased in circulation following MI, suggesting that the influx of CCR2+ HSPCs recruited to cardiac tissues repopulates the myeloid cells needed for tissue repair." (PMID 27123008, 2016). "D6, an important member of the decoy receptor family, binds a broad range of CCR1, CCR2, and CCR5 ligands, prevents excessive infiltration of classical monocytes and neutrophils into the myocardium in a mouse model of myocardial infarction." (PMID 23417922, 2013). "Interestingly, the numbers of both CXCR4+ and KDR+ monocytes increased after myocardial infarction, and their correlation with CD14++CD16+CCR2+ monocytes was more significant." (PMID 40079002, 2025). "A review article on cardiac repair after myocardial infarction reported, that early recruitment of pro-inflammatory monocytes is mediated through activation of the MCP-1/CCR2 axis and that in mice, MCP-1 inhibition exhibits a reduced infarct size and monocyte infiltration." (PMID 36209229, 2022). "Under inflammatory condition, such as myocardial infarction, circulating monocytes will be abundantly recruited to ischemic heart tissues through monocyte chemotactic protein-1 (MCP-1)/CC chemokine receptor 2 (CCR2) interactions." (PMID 31824322, 2019). "Previous studies have shown that circulating monocytes infiltrate the affected tissue in distinct waves after myocardial infarction, with classical Ly6Chi CCR2+ monocytes being responsible for clearance of dead cells and the Ly6Chi CCR2− monocytes for tissue repair." (PMID 30006564, 2018). "Recruitment of the pro-inflammatory Ly-6Chi/CCR2+ subset to inflammatory sites is believed to be CCR2-dependent, since monocytes from CCR2-null mice do not traffic as efficiently into a myocardial infarct as CCR2+ monocytes." (PMID 21159187, 2010).
myocardial infarction (continued). "In other work, the role of CCR2 Val64Ile was not supported in studies of both myocardial infarction and coronary artery disease as diagnosed by angiography in patients versus controls." (PMID 20181074, 2010). "In addition, resident CCR2+ macrophages express different type I IFN-stimulated genes in response to myocardial injury compared with recruited CCR2+ macrophages, suggesting that CCR2+ macrophages respond to type I interferon during myocardial infarction." (PMID 37063966, 2023). "In most models of severe cardiac dysfunction, such as myocardial infarction (MI) or TAC, CCR2-derived macrophages tend to be the predominant cells in the heart following injury." (PMID 35090403, 2022). "Interestingly, although the results of many MI animal experiments showed that disruption of the CCL2/CCR2 axis reduced myocardial infarct size, not all studies had the same conclusion." (PMID 36110847, 2022). "CCR2, the main receptor of CCL2, exhibits mild expression in the human heart, and a single-nucleotide polymorphism of the CCR2 gene is associated with myocardial infarction and heart failure, but not with coronary atherosclerosis, in human patients." (PMID 35260907, 2022). "After ischemic injury due to myocardial infarction (MI), however, the resident CCR2- macrophage subset, while able to proliferate in non-damaged tissues, is lost due to anoxia and nutrient depletion." (PMID 33708206, 2021).
colitis (59 papers, 2011 to 2025). Inflammation of the colon. "For example, SARI, commonly used as a colon cancer inhibitor, has been found to increase CCL2 production when deficient, whereas knocking out CCR2 can block this effect, thereby reducing colitis symptoms." (PMID 39850880, 2024). "In summary, we showed that irbesartan inhibits MCP-1 production and the accumulation of CCR2+ inflammatory monocytes and fibrocytes in the inflamed colon and prevents the development of colitis-associated tumours." (PMID 34620946, 2021). "In a mouse model of colitis-associated carcinogenesis with azoxymethane followed by repetitive administration of dextran sulfate sodium, depletion of Ccr2 (Ccr2 knockout mice) reduced macrophage infiltration and tumor formation in the colonic mucosa." (PMID 27136535, 2016). "A vital role of MCP-1 in the initiation and progression of colitis-associated colon carcinogenesis was demonstrated by using mice deficient in the MCP-1 receptor CCR2 or MCP-1 blocking agent." (PMID 26834744, 2016). "A critical role of MCP-1 in the initiation and progression of colitis-associated colon carcinogenesis was demonstrated by using mice deficient in the MCP-1 receptor CCR2 or MCP-1 blocking agents." (PMID 26167165, 2015). "A pathological role for these elicited Ly6Chi monocytes is evidenced by amelioration of colitis in monocytopenic CCR2-deficient mice 124 and in mice depleted of CCR2-expressing cells." (PMID 24942685, 2014). "A vital role of MCP-1 in the initiation and progression of colitis-associated colon carcinogenesis was demonstrated by using mice deficient in the MCP-1 receptor CCR2 or MCP-1 blocking agents." (PMID 23527025, 2013). "Mice treated with VSL#3 or CLA showed improved DSS colitis that was associated with lower percentages of inflammatory macrophages expressing CCR2 (the receptor for MCP-1) and TNF-α in MLN." (PMID 22363592, 2012). "Interestingly, the homozygous CCR2-deficient mice exhibited earlier onset and more severe colitis compared to their heterozygous counterparts, suggesting that monocytes ameliorate DSS-induced colitis severity during the early phase of disease." (PMID 37153611, 2023). "Our observations suggest that blocking the MCP-1/CCR2 pathway using irbesartan might be beneficial in preventing colitis-associated colon tumours." (PMID 34620946, 2021). "Firstly, monocytopenic CCR2-deficient mice are less susceptible to DSS-induced colitis." (PMID 24726741, 2014). "The proinflammatory roles of CCL2 and its key receptor CCR2 have also been reported in colitis models." (PMID 40749055, 2025). "A recent study showed that CCR2 promotes the migration of monocytes into inflammatory bowel tissue in a mouse model of colitis." (PMID 40472038, 2025). "The recruitment of inflammatory C-C chemokine receptor type 2 (CCR2)+ monocytes to intestinal tissue contributes to disease severity; notably, CCR2 deficiency ameliorates dextran Sulfate Sodium (DSS)-induced colitis in mice." (PMID 40565877, 2025). "The weight loss was significantly decreased in Group 3 (Colitis+GMSCs 2x106) (14.3 ± 4.6 grams) and Group 4 (Colitis+CCR2+GMSCs 2x106) (9.8 ± 2.1 grams) compared to Group 2 (Colitis Model) (19.2 ± 9.1 grams) (p < 0.05 and p < 0.05, respectively)." (PMID 40472038, 2025). "In a dextran sulphate-induced murine model of colitis, F4/80+CD11b+CCR2+Ly6Chigh inflammatory monocytes were recruited to the colon and F4/80+CD11b+CCR2+Ly6Chigh colonic monocyte/macrophages correlated with colonic eosinophilic inflammation." (PMID 38535571, 2024). "Surprisingly, the adoptive transfer of DKI CCR2+ monocytes to WT mice exacerbated colitis severity, with a similar disease progression to the DKI mice." (PMID 37153611, 2023). "Here, we demonstrate that CCR2 is essential for the accumulation of Ly6C+MHCII+ macrophages within the colon of IL10R-deficient mice and that colitis was significantly less severe in these mice." (PMID 35013585, 2022).
colitis (continued). "We previously showed that fibrocytes accumulate in the injured colon of DSS-induced colitis mice through the MCP-1/CCR2 pathway." (PMID 34620946, 2021). "We found that irbesartan suppressed the production of MCP-1, blocked the recruitment of Ly6ChighCCR2+ inflammatory monocytes to the inflamed colon through the MCP-1/CCR2 pathway and inhibited the development of colitis, fibrosis and tumours." (PMID 34620946, 2021). "We previously reported that blocking the MCP-1/CCR2 pathway in the haematopoietic cells ameliorated colitis and prevented intestinal fibrosis during chronic inflammation." (PMID 34620946, 2021). "Although the expression level of CXCR4 did not change, almost all macrophages became highly positive for CCR2 with the development of colitis." (PMID 31189971, 2019). "Relevant to the context of this study, CCR2 has been shown to be increased in patients with inflammatory bowel disease and plays a critical role in inflammatory processes in experimental colitis in mice." (PMID 31320724, 2019). "During colitis, inflammatory macrophages are recruited from blood monocytes in a CCR2-dependent manner, accumulating in the inflamed mucosa and producing pro-inflammatory mediators in the early stages of an immune response." (PMID 29774026, 2018). "During colitis, pro-inflammatory M1 lamina propria macrophages are recruited from Ly6Chi blood monocytes in a CCR2-dependent manner." (PMID 29774026, 2018). "In contrast, during inflammatory conditions such as colitis, Ly6C+ blood monocytes accumulate in a CCR2-dependent manner in the gut lamina propria and locally differentiate further into Ly6C+CX3CR1int monocytes." (PMID 29734661, 2018). "We found that effects of PSMP on colitis were primarily dependent on its influence on monocytes/macrophages and that chemotactic progression relied on CCR2." (PMID 28698550, 2017). "Although the important role of CCR2 in monocytes migrating into the lamina propria and promoting colitis has been proved, the chemokine that controls the earliest-arriving monocytes from the circulation to the lamina propria remains to be discovered." (PMID 28698550, 2017). "Total immune cells (CD45+), myeloid-derived cells (CD11b+), monocytes (CD11b+CCR2+), macrophages (CD11b+F4/80+), neutrophils (CD11b+Ly6G+), and CD11c+ in the colonic lamina propria were detected each day during the induction of colitis." (PMID 28698550, 2017). "Second, administration of an anti-CCR2 depleting antibody, which is presumed to target Ly6Chi monocytes selectively, ameliorates colitis and correlates with lower levels of IL6 and IL1β in colonic tissue." (PMID 24726741, 2014). "Additionally, in colitis models, CCR2 and CD30L expression in monocytes are positively correlated; CD30L drives monocyte homing and differentiation via the CCL2/CCR2 axis and NF-κB pathway, enhancing inflammation." (PMID 39850880, 2024). "In contrast, it has previously been reported that the absence of CCR2 in IL10-deficient mice did not influence colitis severity." (PMID 35013585, 2022). "Furthermore, after 3 days of colitis induction, the gene expression of Ccr1 and Ccr2 was significantly decreased in the animals from the CβGl+ group compared to the rats from the CβG− group." (PMID 35163326, 2022). "CCR2 studies in the CNS of mice with colitis are very limited and require further investigation." (PMID 34983592, 2022). "After 7 days of induced colitis, upregulation of the expression of 22 genes (Ccl2, Ccl3, Ccl4, Ccl5, Ccl6, Ccl7, Ccl12, Ccl17, Cxcl1, Cxcl2, Cxcl6, Cxcl9, Cxcl11, Ccr1, Ccr2, Ccr3, Ccr5, Ccr8, Cxcr2, Csf3, Osm, and Spp1) was observed in the CβG− group compared to the HβG- control group." (PMID 35163326, 2022). "The gene expression of these chemokine receptors (Ccr2, Ccr5, and Cxcr2) in the colitis group fed with feed containing high-molar-mass oat beta-glucan (CβGh+) was significantly lower compared to the CβG− group and was at a similar level as in the control group (HβG−) at both time points." (PMID 35163326, 2022).